IL6 (interleukin 6)
Diseases named in the same sentence as IL6 in open-access papers (continued):
Sharing a sentence is not in itself a finding about the gene and the disease.
tumor (continued). "A tumor epithelial gp130 expression may indicate an activation of the IL-6/gp130/STAT3 pathway, which acts as a tumorigenic factor in PDAC." (PMID 36495330, 2023). "Some factors such as proinflammatory cytokines (IL‐6, IL‐1β, IL‐10, and TNF‐α), reactive oxygen species (ROS), and reactive nitrogen species (RNS) also cause the development of liver tumors by providing tumor microenvironment." (PMID 37576045, 2023). "Tumor-derived IL-6 induces the vascular endothelial growth factor (VEGF) release from CAFs." (PMID 36980785, 2023). "Stromal cytokines, IL-6 in particular, are known to activate tumor cells, but it is hitherto unclear whether and how increased TNBC aggressiveness and chemoresistance are specifically induced by CAFs." (PMID 37173963, 2023). "Moreover, MDSC-derived IL-6 was reported to be partly involved in stimulating tumor cell proliferation." (PMID 37234990, 2023). "Addition of IL-6 to the CM from MSI2-depleted CAFs restored the EMT in NSCLC cells, in parallel with an observed rescue in NSCLC spreading impairment in 2D and 3D invasion assays, thus supporting secreted IL-6 as a key mediator of the tumor-promoting effects of CAFs mediated by MSI2 via EMT." (PMID 37941042, 2023). "Moreover, tumor cells-derived IL-10 and IL-6, transforming growth factor (TGF)-β as well as vascular endothelial growth factor (VEGF) prevent DCs maturation, showing a tolerant phenotype with downregulated expression of costimulatory molecules." (PMID 37007125, 2023). "Treatment with anti-IL6 promoted a decreasing trend in tumor volume and weight." (PMID 36990991, 2023). "In addition, another potential immunomodulator is IL-6, a tumor-suppressive cytokine that promotes tumor cell proliferation and survival in the TME." (PMID 37143088, 2023). "Several cytokines may contribute to tumor progression, particularly IL-1β, TNFα, and IL-6 play key roles in promoting and enhancing EMT." (PMID 37371856, 2023). "Moreover, IL-6 can convert differentiated bulk tumor cells into CSC-like cells in multiple molecular subtypes of BC, providing support for a causal role of IL-6 in tumorigenesis and cancer progression by inducing and/or maintaining cancer stemness." (PMID 36922677, 2023). "IL-6, and IL-8 as immunosuppressive factors may stimulate tumor cells growth, contribute to loco-regional relapse and metastasis that might be utilized as a marker for immunity status and monitoring of the course of tumor." (PMID 36693957, 2023). "Indeed, our data show an increase in the expression of genes involved in immune response and chemotaxis (e.g., Il6, Cxcl, and Ccl genes), as also detected in LECs stimulated with tumor-derived conditioned medium." (PMID 37686421, 2023). "Consistent with the literature, exogenous IL-6 supplementation in LOC339059 cells could partially restore the PDL1 expression in tumor cells." (PMID 38001573, 2023). "Moreover, both TNC and CCL2 tumor levels correlated negatively with markers of M1 macrophage status (IL6) and positively with markers of M2 macrophage status (CD168 and Arg1), with a higher correlation of TNC than CCL2 at both 3 and 11 weeks." (PMID 37176074, 2023). "In the non–tumor-bearing experiment, changes in cytokine concentrations in the marrow showed trends similar to the plasma, which increased or remained relatively constant over the 14 days of treatment with the exception of IL6." (PMID 36968140, 2023). "IL-6 levels usually strongly correlate with tumor size, stage, and progression of cancer." (PMID 38313431, 2023). "A combination of transforming growth factor beta (TGF-β) and interleukin-6 (IL-6) induces Th17 cell activation, which results in the promotion of angiogenesis and tumor progression, but the effects of Th17 cells remain unclear." (PMID 38550850, 2023).
tumor (continued). "Interestingly, HNSCCs constitute a tumour environment that promotes Th17 cell activity due to the release of IL-23 and IL-6 by the neoplastic cells themselves and by TIL and IL-1β by immune cells infiltrating the cancer niche." (PMID 36980527, 2023). "GSEA results suggest that high CHI3L1 expression is associated with biological processes involved in cytokine production (IL-2 and IL-6), mTORC1 and complement signaling, interferon-γ response, and inflammatory response, leading to an immunosuppressive effect in the tumor microenvironment." (PMID 37185706, 2023). "Thereafter, we constructed tumor xenograft mouse models to validate the effect of IL-6 on EMT." (PMID 36814597, 2023). "In addition, T stage, N stage, TNM stage, adjuvant chemotherapy, CD163 cell infiltration, IL-6 expression, and tumor SUV were significant prognostic factors for RFS (p < 0.05)." (PMID 36983926, 2023). "Together, these results yielded a conceptual model whereby IDO1 acts as a regulatory node at the interface between IFNγ and IL6, shifting the inflammatory microenvironment to a tumor-promoting state by preventing the ability of IFNγ to pare back the tumor neovasculature." (PMID 37182174, 2023). "IL-6 plays a crucial role in boosting T-cell trafficking to lymph nodes and tumor sites." (PMID 37445686, 2023). "This may be distinct from the role of IL-6 as a direct driver of STAT3 activation in the tumor microenvironment." (PMID 38022653, 2023). "Thus, lower IL-6 secretion by TAMs as a result of their interaction with lower C1GalT1 expressing tumour cells will likely have a less positive influence on tumour growth in the TME." (PMID 37612278, 2023). "This could be attributed to a cumulative effect of prolonged EHop-016 treatment or additional contribution from cells in the tumor microenvironment, as well as other IL-6 releasing cells such as fibroblasts, in these immunocompromised mice." (PMID 37397366, 2023). "Accordingly, they concluded that IL-6 might facilitate tumor growth and confer immunotherapy resistance through tumor cell polarization and expansion of the Th22 cell population." (PMID 37835465, 2023). "Therefore, the goal of this review is to highlight the importance of custom therapeutic strategies for HCC patients, taking into consideration the dynamic nature of the interactions between Il-6 and the tumor microenvironment." (PMID 37892997, 2023). "In fact, IL-6 in a normal environment helps to stabilize the senescent state, through an autocrine manner, while in an environment where there are tumor cells, it promotes the epithelial-mesenchymal transition favoring the spread of tumor cells." (PMID 37175861, 2023). "Additionally, some cytokines including TGF-β, IL-10 and IL-6 were described to facilitate tumor escape." (PMID 37340387, 2023). "There are distinct roles of IL‐6 in modulation of tumour growth." (PMID 36419386, 2023). "Therefore, CAFs would mediate tumor immunosuppression by regulating hypoxia-pseudohypoxia-mediated HIF1α activation via IL-6." (PMID 36764954, 2023). "Notably, HERC2-positive tumor cells expressed higher IL-6/JAK/STAT3-related genes and STAT3-targeted genes than HERC2-negative tumor cells, which also indicated the regulatory role of HERC2 in JAK2/STAT3 signaling." (PMID 36721234, 2023). "IL-1β and IL-6 correlate with the tumor extent and with the presence of lymph nodes." (PMID 38137862, 2023). "In the investigation for CAFs and CD8+ or forkhead box protein 3 tumor-infiltrating lymphocytes by IHC, it was revealed that IL-6 blockade, or targeting CAFs, may improve preexisting tumor immunity and enhance the efficacy of conventional immunotherapies." (PMID 36572816, 2023). "IL-6 has been proven to promote tumor angiogenesis and enhance tumor metastasis and invasion." (PMID 36992837, 2023).
tumor (continued). "Notably, the presence of a CREB-binding site in the IL-6 promotor region together with the high expression of CREB triggered by the EWSR1::CREB1 fusion has been proposed to explain the IL-6 overexpression observed in this rare tumor type." (PMID 36690805, 2023). "Finally, the role of cancer associated microbiota should be considered as well in the disruption of retinol metabolism and the increase in tumor-promoting IL-6." (PMID 37185128, 2023). "Meanwhile, several preclinical studies also revealed that incomplete ablation could promote tumor progression and tumor angiogenesis via the IL-6/HGF/c-Met pathway, the HGF/c-Met/STAT3 pathway, and the upregulation of VEGF." (PMID 36831664, 2023). "Because whole tumor lysates were used to measure the concentrations of lactate and IL-6 in the current study, cell type–specific measurements by purification of CAFs and tumor cells from tumors will further support the role of lactate-stimulated CAFs in fostering an immunosuppressive TME." (PMID 37733442, 2023). "Various tumor cells were also reported to express angiogenesis factors under the hypoxic condition to favor tumor progression, such as IL-6, MMPs, VEGF and hypoxia-inducible factor (HIF)-1α, and IL-37 treatment was proven to prevent tumor cells from producing such factors." (PMID 37928545, 2023). "Several factors including IL-6 and IL-8 are secreted from CAFs into the tumor microenvironment." (PMID 36980785, 2023). "IL-6 signaling may also facilitate tumor survival, proliferation, migration, as well as chemoresistance, which contribute to tumor progression and poor outcomes in cancer patients." (PMID 37047623, 2023). "IL-6 enhances tumor progression by inducing a less mature phenotype of macrophages." (PMID 37108179, 2023). "The expression level in HNSCC tumour tissue is low, and inhibition of the IL-6 downstream signalling pathway may enhance the therapeutic effect on tumours with elevated IL-6 levels." (PMID 36600313, 2023). "Additionally, IL-6 and IL-8 can spread senescence in the surrounding cancer cells in a paracrine way, helping further tumor suppression." (PMID 38275386, 2023). "Further, IL-6 can induce activation of the PI3K/AKT pathway in resistant tumor cells." (PMID 37046703, 2023). "Having established PRMT6’s capacity to regulate the IL-6/STAT3 signaling pathway—an essential player in tumor metastasis—it was imperative to delve deeper into whether PRMT6-mediated tumor metastasis hinged on the IL-6/STAT3 signaling pathway." (PMID 37813837, 2023). "Another pro-inflammatory cytokine, IL-6 polarize the tumor microenvironment towards Th1 type." (PMID 37122749, 2023). "Tumor-associated macrophages (TAMs), by secreting many factors, such as TGF-B, TNF-a, IL-1B, and IL-6, may be responsible for inducing the EMT process in CRC." (PMID 37185706, 2023). "However, IL-6 shows an important tumor-suppressor effect based on the activation, expansion and survival of effector lymphocytes." (PMID 36851213, 2023). "Inflammatory cytokines, such as IL-6, can take part in the regulation of tumor activity." (PMID 36612282, 2022). "The evidence poses a challenge for tumor-targeted therapeutic strategies targeting IL6." (PMID 36506508, 2022). "Furthermore, CD163+ functional TAMs can be developed in tumor-bearing IL-6 transgenic mice and have produced high levels of immunosuppressive molecules, such as arginase-1 (Arg-1), IL-10, and VEGF." (PMID 35740551, 2022). "Furthermore, hyperthermia accelerates cytotoxic T cell recruitment into the tumor microenvironment by IL-6 trans-signaling-mediated tumor vasculature remodeling." (PMID 35246220, 2022). "These tumor-promoting effects support the rational to therapeutically target IL-6." (PMID 36436127, 2022). "However, there are also reports that IL6 is an inhibitor of tumor cell growth, which functions to inhibit tumor cell growth by activating the anti-tumor T cell immune response." (PMID 36142828, 2022).
tumor (continued). "Under conditions of chronic inflammation, IFN-γ secretion by Th1 lymphocytes seems to play a pivotal role in preventing tumor cell proliferation, while IL-13 derived from Th2 lymphocytes and TNF-α, IL-6, and IL-17 produced by Th17 cells promote dysplastic cell proliferation and tumor growth." (PMID 35264972, 2022). "The role of IL-6 in promoting angiogenesis in tumor tissues is closely related to VEGF." (PMID 36091401, 2022). "On the other hand, CAFs can secrete multiple chemokines and cytokines, such as transforming growth factor-β (TGFβ), CC-chemokine ligand 2 (CCL2), and interleukin-6 (IL-6), in order to recruit immunocytes with inhibitory functions in the tumor stroma, thereby facilitating immune evasion." (PMID 35198057, 2022). "IL6 can have distinct effects on cells, both in promoting population expansion as well as promoting cellular senescence, hence it is an important component both in normal pituitary regulation as well as the formation of tumours." (PMID 36451046, 2022). "Elevated levels of G-CSF, IL-6 and CXCL13, and B cell counts were associated with 4T1 growth, whereas CCL17, CXCL10, total myeloid cells, CCL2, IL-10, CXCL1, and Ly6Cintermediate monocytes were associated with CT26 tumour development." (PMID 35226704, 2022). "Moreover, BM-MSCs secrete interleukin 6, which stimulates cancer cells to induce the mobilization of tumor endothelial cells and tumor vessel formation." (PMID 36230633, 2022). "Tumor growth was significantly reduced in IL-6-/- mice when compared to WT mice." (PMID 36405719, 2022). "In addition, the potential predictive value of baseline concentration of IL-6 in plasma and tumor tissues for PFS was confirmed with areas under the curve (AUCs) of 0.779 and 0.790, respectively." (PMID 35550592, 2022). "The observation of complete tumor regression in this context suggests that at least transient up-regulation of IL-6 may be beneficial to generate robust anti-tumour responses." (PMID 36532027, 2022). "It was reported that trabectedin has dual effects on anticancer including inducing the differentiation and apoptosis of malignant cells and regulating the tumor microenvironment by limiting the associated inflammatory mediator production such as CCL2, interleukin-6, and VEGF." (PMID 36438821, 2022). "On the other hand, IL-6 could present an anti-tumor function by inducing the transformation of CD8+ T cells into highly cytotoxic cells." (PMID 35681617, 2022). "Studies have shown that tumor cells in the CNS can secrete macrophage migration inhibitory factor, IL-8, and plasminogen activator inhibitor 1, thereby activating astrocytes; activated astrocytes can secrete IL-6 and tumor necrosis factor-α (TNF-α)." (PMID 36338717, 2022). "Moreover, activated STAT3 motivates the secretion of many chemokines and cytokines such as, IL-6 and IL-16 to maintain activation of immune cells in the tumor tissue." (PMID 36374927, 2022). "Notably, in these mice, overexpression of IL-1 and IL-6 lowered overall survival and resulted in more aggressive tumor growth." (PMID 35159388, 2022). "Furthermore, paracrine IL-6 triggered by surrounding folliculo-stellate cells is capable of stimulating tumour development." (PMID 35837315, 2022). "The first was inflammation-related pathways, such as the IL6/JAK/STAT3 signalling, inflammatory response, IL2/STAT5 signalling, TNF-alpha signalling via NFKB, and KRAS signalling pathways, which have been proven to be associated with tumours." (PMID 35246158, 2022). "In the 1970s, although there was not yet a methodology with sufficient sensitivity to measure these cytokines in cancer patients and obtain consistent results, treatment with anti-TNF- and IL-6 antibodies was proven to be effective in reducing cachexia in mouse tumor models." (PMID 36072935, 2022). "Here, we investigated whether IL-6-induced STAT3 activation can reverse the anti-tumor effect of Stattic in PCCs." (PMID 35288541, 2022).
tumor (continued). "In addition, MB cells that had been co-cultured with microglia for three days was found to secrete significant quantities of IL-6, which now constitute a cytokine of tumor cell origin that can signal in autocrine fashion." (PMID 35159191, 2022). "Moreover, the degree of tumor IL-6 levels is inversely correlated with the cancer prognosis and aggressiveness, through manipulation of extracellular matrix proteins and cancer-associated fibroblasts." (PMID 35269343, 2022). "Moreover, pharmacological inhibition or genetic inactivation of the IL-6/STAT3 pathway inhibits the invasive capacity of tumor cells, and hence, prevents metastatic colonization in PDAC." (PMID 35993361, 2022). "Additionally, hypothalamus functions are impaired during cancer cachexia where tumor-induced cytokines such as TNFα, interferon gamma, IL-1, and IL-6 stimulate anorexigenic, and inhibit orexigenic pathways." (PMID 35441960, 2022). "As MLL-tumors express high levels of IL6, IL1β and TNFα9, changes in the liver could be related to a tumor-induced acute phase response." (PMID 35551231, 2022). "PBMC co-cultured with tumor cells produced high amount of IL-6 and TNF-α than PBMC alone." (PMID 35444660, 2022). "In addition to SDF-1, fibroblast-derived IL-1β/IL-6, tumor cell-derived-IL-8, and tumor-infiltrated lymphocyte-derived-TNF-α were upregulated in OSCC patients with high TNM stage." (PMID 36045118, 2022). "In return, activated TAMs increase tumor cell migration by secreting IL-6." (PMID 35345849, 2022). "We are unaware of any other reports indicating that tumor-derived IL-6 could have such a broad, suppressive (or distractive) effect on Th populations." (PMID 36142210, 2022). "Recently, IL-6 has received increasing attention as a vital cytokine involved in tumor invasion." (PMID 36531024, 2022). "IL6 is one of the most important cytokine families in tumor occurrence and metastasis." (PMID 35672352, 2022). "We next explored whether anti-IL-6 combined with NVP-BEZ235 enhanced the inhibition of tumour cell proliferation." (PMID 35165269, 2022). "A higher level of only the cytokine IL-6 was significantly correlated with the tumor burden." (PMID 35013456, 2022). "In contrast, plasma IL-6 level had no direct association with 4T1 tumour size, but correlated positively with factors that did, namely plasma G-CSF and CXCL13 levels." (PMID 35226704, 2022). "Inhibiting IL-6 derived from macrophages reverses tumor progression." (PMID 35062950, 2022). "IL-6 antibody treatment inhibits in vitro cell proliferation and in vivo tumor growth in both ER+ MCF7 cells and TNBC, MDA-MB-231 cells through a blockade of STAT3 activation and associated downregulation of STAT3 target genes including SOCS3, IL6ST and genes involved in angiogenesis." (PMID 35053592, 2022). "Therapeutic strategies to mitigate neutrophil-CAF-tumor cell IL-1β/IL-6/STAT-3 signaling during NAC may improve pathologic responses and/or survival in PDAC." (PMID 36107485, 2022). "We were curious if IL-6-mediated METTL3 acetylation contributes to tumor invasiveness." (PMID 36289222, 2022). "In turn, EVs isolated from GC cells facilitate TAMs recruitment by activating NF-kB signaling in GC-MSCs while enhancing the phagocytic function of TAMs, upregulating IL-6 and IL-8 secretion, indicating the existence of a feedback loop between tumor cells and TA-MSCs." (PMID 35842634, 2022). "In addition to endocrine disorders, immuno-inflammatory responses such as adipose tissue releases proinflammatory cytokines such as TNF-α or IL-6, which promote angiogenesis and cell proliferation leading to rapid tumor growth." (PMID 35463353, 2022). "Thus, the dysregulated/enhanced IL-6 gene expression in neoplastic, stromal, or tumor-adjacent immune cells and IL-6-driven cell proliferation contribute to increased aggressiveness of certain neoplastic diseases." (PMID 35406728, 2022).